HHLA2 (HHLA2 member of B7 family)
Diseases named in the same sentence as HHLA2 in open-access papers (continued):
Sharing a sentence is not in itself a finding about the gene and the disease.
gallbladder cancer (6 papers, 2019 to 2025). "Still, more studies with a higher number of samples should be encouraged to elucidate HHLA2’s significance in gallbladder cancer." (PMID 38786018, 2024). "For instance, gallbladder cancer, which typically shows a limited response to anti-PD-L1 therapy, often expresses higher levels of HHLA2 than PD-L1, suggesting that targeting HHLA2 could be a viable therapeutic strategy." (PMID 40255615, 2025). "Altogether, HHLA2 is a promising target for immunotherapy in gallbladder cancer." (PMID 38786018, 2024). "Notably, in conditions such as ccRCC and gallbladder cancer, HHLA2 seems to be a better target for immunotherapy than PD-L1, which is already in use in cancer therapies." (PMID 38786018, 2024). "Studies show that HHLA2 could play a significant role in gallbladder cancer (GBC) as well." (PMID 38786018, 2024). "Moreover, HHLA2 expression in GBC was more prominent than PD-L1 expression, suggesting that it could be a better therapeutic target in gallbladder cancer than PD-L1." (PMID 38786018, 2024). "For example, results of a previous study suggested that HHLA2 is up-regulated in gallbladder cancer, and increased expression of HHLA2 may indicate poor prognosis; moreover, the destiny of CD8+ TILs was also significantly reduced with increased expression of HHLA2." (PMID 38762741, 2024).
lymph node metastasis (6 papers, 2018 to 2025). "In contrast, another study linked HHLA2 to lymph node metastasis and poor overall survival, observing high expression only in stromal cells." (PMID 40255615, 2025). "In bladder urothelial carcinoma, HHLA2 expression is an independent risk factor for lymph node metastases." (PMID 38786018, 2024). "Interestingly, the high expression of HHLA2 in the stromal compartment was associated with more prominent lymph node metastasis (p = 0.002), distance metastasis (p = 0.049), and more advanced FIGO Stage (p = 0.045)." (PMID 38786018, 2024). "Furthermore, high HHLA2 expression was associated with old age (OR = 1.30, 95% CI: 1.03–1.63), lymph node metastasis (OR = 1.99, 95% CI: 1.41–2.81), and vascular invasion (OR = 1.69, 95% CI: 1.18–2.42)." (PMID 34397730, 2021). "There was a significant positive correlation between high HHLA2 expression and clinicopathological characteristics including tumor size, multiplicity, higher clinical stage, high grade, and lymph node metastasis." (PMID 38786018, 2024). "Notably, high levels of the HHLA2 protein correlate with increased tumor size and stage, lymph node metastasis and lower rates of relapse-free and overall survival in affected patients." (PMID 40255615, 2025). "Higher HHLA2 expression could also be found in triple negative breast cancer patients at stage I to III, and significantly associated with lymph node metastasis and poorer prognosis." (PMID 31015801, 2019). "HHLA2 was significantly elevated in BUC and significantly correlated with cancer size, stage, grade, and the presence of lymph node metastasis; HHLA2 can be used independently to predict BUC prognosis." (PMID 41315192, 2025).
kidney cancer (5 papers, 2019 to 2025). Primary or metastatic malignant neoplasm involving the kidney. "The immune checkpoint HERV-H LTR-associating 2 (HHLA2) is expressed in kidney cancer and various other tumor types." (PMID 37891555, 2023). "HHLA2 expression in kidney cancer exhibits differential regulation between in vivo and in vitro settings." (PMID 37891555, 2023). "HHLA2 expression is induced on kidney cancer cells in vivo by a tumor microenvironmental signal that is not present in vitro." (PMID 37891555, 2023). "HHLA2 expression is differentially regulated in kidney cancer epithelial cells and monocytes." (PMID 37891555, 2023). "Interestingly, HHLA2 expression in kidney cancer cells is induced by TME signals in vivo but not in vitro, while monocytes can express HHLA2 in response to certain cytokines, particularly IL-10." (PMID 40255615, 2025).
pancreatic adenocarcinoma (5 papers, 2018 to 2025). "Aydın and Turhan examined HHLA2 expression in adenocarcinomas of the pancreas, ampulla and distal bile duct." (PMID 40255615, 2025). "We found that HAVCR1 was associated with HHLA2, CD44 and TNFRSF4 in Liver hepatocellular carcinoma and Pancreatic adenocarcinoma." (PMID 35754803, 2022). "Although this study suggests that loss of HHLA2 may contribute to immune evasion of pancreatic adenocarcinoma, it does not provide a direct correlation with clinical prognosis or specific survival outcomes." (PMID 40255615, 2025). "Furthermore, HAVCR1 expression was correlated with other immune molecules such as HHLA2 (Human endogenous retrovirus-H long terminal repeat-associating protein 2), CD44 and TNFRSF4 (TNF Receptor Superfamily Member 4) in Liver hepatocellular carcinoma and Pancreatic adenocarcinoma." (PMID 35754803, 2022). "On the contrary, Yan et al26 recently reported no or weak HHLA2-expression in normal pancreas tissue, but prevalent expression in pancreatic adenocarcinoma." (PMID 32071413, 2020).
pancreatic ductal adenocarcinoma (5 papers, 2021 to 2025). An infiltrating adenocarcinoma that arises from the epithelial cells of the pancreas. "Nevertheless, high HHLA2 expression was associated with better OS in patients with pancreatic ductal adenocarcinoma (HR = 0.45, 95% CI: 0.32–0.64)." (PMID 34397730, 2021). "In pancreatic ductal adenocarcinoma, HHLA2 is associated with better survival rates and acts as a co-stimulatory ligand." (PMID 33962626, 2021). "Conversely, in gliomas and pancreatic ductal adenocarcinomas, tumors with high levels of HHLA2 expression had a better prognosis, suggesting that it may act as a co-stimulator through the TMIGD2 pathway." (PMID 37261362, 2023). "However, some studies have suggested that high HHLA2 expression is an independent predictor for better survival of pancreatic ductal adenocarcinoma and ccRCC." (PMID 36003385, 2022).
ampullary cancer (4 papers, 2020 to 2023). "The wide expression of HHLA2 in tumour cells and its association with cancer recurrence and patient survival suggest that HHLA2 represents a relevant immune checkpoint molecule in pancreatic and ampullary cancers." (PMID 32071413, 2020). "In pancreatic and ampullary cancers, 50 % of patients with low expression of HHLA2 had poorly differentiated cancer, while about 18 % of highly expressed HHLA2 cases had this cancer phenotype." (PMID 38144305, 2023). "This study is the first to show that HHLA2 is widely expressed in tumour cells of patients with ampullary cancer of the pancreato-biliary subtype." (PMID 32071413, 2020). "In addition, we demonstrate that HHLA2 mRNA was expressed, although at variable levels, in all pancreatic and ampullary cancers examined." (PMID 32071413, 2020). "However, increased HHLA2 expression was associated with better post-surgical prognosis in pancreatic and ampullary cancers when using a different anti-HHLA2 antibody clone for IHC." (PMID 32509772, 2020). "Therefore, our data on the biological significance of HHLA-2 expression in ampullary cancer require validation in a larger, probably multi-centre cohort of this type of cancer." (PMID 32071413, 2020). "Whether HHLA2 is expressed in ampullary cancer is as yet unknown." (PMID 32071413, 2020). "Its association with cancer recurrence and patient survival suggest that HHLA2 may represent a biologically relevant immune checkpoint molecule in these cancer types and should be evaluated as a potential target for immunotherapy in pancreatic and ampullary cancers." (PMID 32071413, 2020). "This analysis indicates that HHLA2 expression in tumour cells is, independent of clinical or pathological characteristics, predictive for survival after tumour resection in a combined cohort of pancreatic and ampullary cancer patients." (PMID 32071413, 2020).
bladder urothelial carcinoma (4 papers, 2020 to 2024). "Other enriched genes we found (AR, GNB3, HHLA2 and IL4) were related to transitional cell carcinoma of the bladder (also known as Urothelial carcinoma)." (PMID 35565241, 2022).
lung adenocarcinoma (4 papers, 2021 to 2024). A carcinoma that arises from the lung and is characterized by the presence of malignant glandular epithelial cells. "In lung adenocarcinoma, there is a significant association between high TILs infiltration and HHLA2 expression after adaptation to the mutated state." (PMID 35287670, 2022). "The increased expression of HHLA2 in lung adenocarcinoma was detectable mainly in the tumor cell cytoplasm and membrane." (PMID 38786018, 2024). "A positive correlation between M2 macrophage infiltration and HHLA2 expression in lung adenocarcinoma was identified in TIMER database." (PMID 34152094, 2021). "Additionally, the TIMER database uncovered a correlation between higher M2 macrophage infiltration and increasing HHLA2 expression in lung adenocarcinoma." (PMID 38786018, 2024). "This suggests that different factors may be involved in TIL recruitment, and HHLA2 expression may be at least partially involved in TIL infiltration in lung adenocarcinoma." (PMID 35287670, 2022). "HHLA2 was highly expressed in lung adenocarcinoma and squamous cell carcinoma." (PMID 34152094, 2021). "Numerous studies have shown that HHLA2 is upregulated in non-small cell lung carcinoma (NSCLC) including squamous cell carcinoma, lung adenocarcinoma (LUAD), and pulmonary sarcomatoid carcinoma (PSC)." (PMID 38786018, 2024). "TCN1 is closely related to the molecular targets of lung adenocarcinoma BRAF, HHLA2, and CD274 (PD-L1), especially BRAF and HHLA2." (PMID 35287670, 2022).
metastatic disease (4 papers, 2016 to 2023). "The HHLA2 gene, however, was highly expressed in BMDMs of MD-susceptible line 72, which presumably implicates it in a novel immunosuppressive mechanism within the microenvironment of metastatic disease." (PMID 30678299, 2019). "HHLA2 expression was detected at higher levels in metastatic specimens and correlated with metastatic disease and poor survival, suggesting that HHLA2 contributes to immunosuppression." (PMID 37424864, 2023). "Overall, 68% of tumors expressed HHLA2, with 87%, 54%, and 93% expressing HHLA2 in the biopsy specimens, definitive surgery specimens, and metastatic disease specimens, respectively." (PMID 27531281, 2016). "HHLA2 was expressed in almost all metastatic disease specimens and was more prevalent than in primary specimens without known metastases (93% vs 53%, p = 0.02)." (PMID 27531281, 2016). "It is interesting that HHLA2 expression is higher in both primary tumors with metastatic disease and in metastatic tissues compared to primary tissue without metastatic disease." (PMID 27531281, 2016). "An additional two specimens obtained at the time of initial biopsy, 17 specimens obtained at the time of definitive surgery, and five metastatic tumor specimens were available for analysis of HHLA2 and TILs, did not have either associated clinical outcome or demographic data." (PMID 27531281, 2016). "HHLA2 was greater in primary tumors from patients with the presence of metastatic disease compared with samples from patients without metastatic disease; however, this was not statistically significant (78% vs 53%, p = 0.17)." (PMID 27531281, 2016). "HHLA2 expression was significantly greater in metastatic tissue compared to tumors from the primary tumor in patients without metastatic disease (93% vs 53%, p = 0.02)." (PMID 27531281, 2016). "HHLA2 expression was quantified as the percentage of positive tumor cells on the TMA by IHC and categorized as tumor specimens obtained at the time of initial biopsy, at the time of definitive surgery, or from metastatic disease." (PMID 27531281, 2016). "However, as previously noted HHLA2 expression was higher in metastatic tissue compared to primary tumor without metastatic disease (93% vs 53%, p = 0.02)." (PMID 27531281, 2016). "Given the high prevalence of HHLA2 expression in metastatic tissue, the relationship between HHLA2 expression in specimens from patients’ primary site of disease was compared with the presence or absence of metastatic disease." (PMID 27531281, 2016).
thyroid cancer (4 papers, 2022 to 2025). "In thyroid cancer, particularly PTC, HHLA2’s role as a tumor promoter and its association with aggressive disease features highlight its potential as a therapeutic target." (PMID 40255615, 2025). "On the other hand, studies on thyroid cancer and neuroendocrine tumors highlighted HHLA2’s significance in disease progression, indicating poor prognosis and its association with metastasis." (PMID 40255615, 2025).
triple-negative breast carcinoma (4 papers, 2019 to 2021). An invasive breast carcinoma which is negative for expression of estrogen receptor (ER), progesterone receptor (PR), and human epidermal growth factor receptor 2 (HER2). "But in triple-negative breast cancer (TNBC), overexpressed HHLA2 was linked to lymph node positivity." (PMID 34181347, 2021).
intraductal papillary mucinous neoplasms (3 papers, 2018 to 2025). "In intraductal papillary mucinous neoplasms (IPMN; n = 4), HHLA2 expression varied with pathological grade, showing strong staining in moderate-grade ducts, while high-grade IPMN lesions exhibited moderate staining." (PMID 40255615, 2025). "In the independent intraductal papillary mucinous neoplasm (IPMN) cohort, 70.73% of cases expressed HHLA2, but this expression was not markedly related to IPMN grade." (PMID 38786018, 2024).
prostate carcinoma (3 papers, 2022 to 2024). A carcinoma that arises from epithelial cells of the prostate gland. "A previous study established a new immune scoring system, the B7 score, based on the expression of B7-H3 and HHLA2, which played a vital role in predicting the prognosis of prostate cancer." (PMID 36159808, 2022). "A previous study established an B7 score based on B7-H3 and HHLA2 expression, which played a significant predictive value for prostate cancer." (PMID 36159808, 2022). "The simultaneous overexpressing proportion of B7-H3 and HHLA2 was between 18% and 31% in the prostate cancer tissues." (PMID 36159808, 2022).
renal carcinoma (3 papers, 2019 to 2024). A carcinoma arising from the epithelium of the renal parenchyma or the renal pelvis. "Prognostic models suggest that HHLA2 downregulation is a sign of increased immunosuppressive responses, meaning that HHLA2 plays an important role in enhancing immunological activity against tumor cells in renal cancer." (PMID 38786018, 2024). "HHLA2’s role in renal cancers has been extensively evaluated." (PMID 38786018, 2024). "Further studies in this area are of high importance as not only is HHLA2 a potential target for immunotherapy in renal cancer, but epigenetic changes related to its expression may also be valuable in the therapeutic context." (PMID 38786018, 2024).
spinal chordoma (3 papers, 2021 to 2024). A slow-growing malignant bone tumor arising from the remnants of the notochord and occurring in the spine. "Similar findings regarding the dual blockade of PD-L1 and HHLA2 have also been reported in spinal chordoma patients." (PMID 38553708, 2024). "Here, we aimed to determine the expression of PD-L1, HHLA2, B7H3, IDO-1 and Galectin-9 in spinal chordoma and evaluated their association with tumor infiltrating lymphocytes (TILs), clinicopathological characteristics and survival of patients." (PMID 35145510, 2021). "The present study objectively measured the tumoral and stromal expression of PD-L1, HHLA2, B7H3, IDO-1 and Galectin-9 in spinal chordoma tissues and analyzed their relationship with the clinical data of patients." (PMID 35145510, 2021). "In this study, we sought to objectively measure the expression of PD-L1, HHLA2, B7H3, IDO-1 and Galectin-9 in spinal chordoma tissues by multiplexed quantitative immunofluorescence (QIF)." (PMID 35145510, 2021). "In this study, we objectively analyzed the expression and coexpression of PD-L1, HHLA2, B7H3, IDO-1 and galectin-9 in spinal chordoma tissues and investigated the clinical impact of these immune checkpoints." (PMID 35145510, 2021).
chordoma (2 papers, 2021 to 2022). Chordomas are rare malignant tumors arising from embryonic remnants of the notochord in axial skeleton. "The precise mechanism underlying the relationship between tumoral HHLA2 expression and chordoma prognosis remains unknown." (PMID 35145510, 2021). "We observed a high coexpression rate (64/92) for tumoral HHLA2 and PD-L1 in chordoma tissues, whereas other markers were infrequently coexpressed in this region." (PMID 35145510, 2021). "We found that the HHLA2 protein was widely expressed in chordoma tissues and that tumoral HHLA2 levels significantly affected the survival of patients." (PMID 35145510, 2021). "Altogether, whether HHLA2 affects chordoma biology and patient outcome through TMIGD2 signaling or other molecular pathways to inhibit antitumor immune responses deserves further confirmation." (PMID 35145510, 2021). "The effects of many immune checkpoints, including LAG3, TIM3, SIRPα, HHLA2, MAGEA4, VISTA and TIGIT, have been validated in chordoma, and five of them (TIM3, SIRPα, HHLA2, MAGEA4 and VISTA) were only evaluated in preclinical study." (PMID 36612259, 2022). "Similarly, we found that tumor HHLA2 expression was related to suppressive antitumor immunity (specifically including reduced CD8+ TIL density and increased PD-1+ T cell levels) in the chordoma microenvironment." (PMID 35145510, 2021). "Moreover, future works are needed to explore the expression pattern and biological functions of the respective ligands of PD-L1 and HHLA2 (namely, PD-1 and CD28) in chordoma tissues." (PMID 35145510, 2021).
colon cancer (2 papers, 2022 to 2023). "On the contrary, we found a negative correlation between HHLA2 tumor concentration factor 1 from principal component analysis containing: HGF, M-CSF, b-NGF, SCGF-b, IL-7, FGFbasic, G-CSF, PDGF-bb, VEGF, GM-CSF, and trophic factors, which can be produced by colon tumor cells." (PMID 36982953, 2023).
malignant glioma (2 papers, 2021 to 2022). A grade III or grade IV glioma arising from the central nervous system. "The tumor‐infiltrating immune cell model showed that HHLA2 was negatively associated with TAMs in malignant glioma, indicating that the importance of association between HHLA2 and TAMs." (PMID 34152094, 2021).
oral squamous cell carcinoma (2 papers, 2019 to 2024). "In this study, we used oral squamous cells carcinoma (OSCC) tissue microarrays and immunohistochemistry methods to investigate the expression patterns of HHLA2 and TMIGD2 in OSCC." (PMID 31089395, 2019).
squamous cell carcinoma (2 papers, 2021). A carcinoma arising from squamous epithelial cells. "We studied HHLA2 expression in NSCLC (adenocarcinoma, squamous cell carcinoma, and large cell undifferentiated carcinoma) and SCLC." (PMID 34181347, 2021).
upper tract urothelial carcinoma (2 papers, 2023 to 2024). "In upper tract urothelial carcinoma (UTUC), elevated expression of HHLA2 in tumor cells was associated with lower histological grade, lower NLR, and negative lymphovascular invasion, while higher HHLA2 expression in stromal cells correlated with a higher histological grade." (PMID 38786018, 2024).
urothelial carcinoma (2 papers, 2022 to 2024). A malignant neoplasm derived from the transitional epithelium of the urinary tract (urinary bladder, ureter, urethra, or renal pelvis). "More research on the role of HHLA2 in urothelial carcinoma would be beneficial." (PMID 38786018, 2024). "There are also reports concerning HHLA2 function in urothelial carcinoma." (PMID 38786018, 2024).
adenoma (1 paper, 2024). A neoplasm arising from the epithelium. "Among them, two up-regulated (ADAM12, CEMIP) and one down-regulated (HHLA2) hub-genes have not been majorly highlighted for their contribution to adenoma-carcinoma transition, to the best of our knowledge." (PMID 38698020, 2024).